ERBB3 (erb-b2 receptor tyrosine kinase 3)
Diseases named in the same sentence as ERBB3 in open-access papers (continued):
Sharing a sentence is not in itself a finding about the gene and the disease.
prostate carcinoma (continued). "The ERBB3 mRNA level was dramatically higher in bladder, colorectal, kidney, lung, ovarian, and prostate cancer tissues and significantly lower in the brain and CNS, esophageal, head and neck, lymphoma, myeloma, and sarcoma cancers compared with the corresponding normal tissues." (PMID 33732282, 2021). "To date, most studies have associated ErbB3 and sErbB3 with breast and prostate cancers and there has been no report coupling these mediators with systemic inflammatory or gastrointestinal diseases in human." (PMID 22606320, 2012). "ErbB3 and other members of the EGFR family have been implicated in cancer progression, it however remains unknown whether Ebp1 participate in prostate cancer progression in vivo." (PMID 19025630, 2008). "Since the expression of Ebp1 correlated with prostate cancer progression, we also evaluated whether the expression of Ebp1 correlated with the nuclear expression of Ebp1 regulated proteins (AR, Cyclin D1 & ErbB3) and the proliferation marker Ki67." (PMID 19025630, 2008). "In support of this possibility, a recent study using a dual EGFR/HER2 kinase inhibitor in prostate cancer cell lines showed that an HER2/ERBB3 signalling pathway protected the AR from degradation at low androgen concentrations through an AKT-independent pathway." (PMID 17211467, 2007). "ErbB3 has not been as extensively studied, but analysis of clinical prostate cancer specimens indicates that overexpression of ErbB3 has been linked to a less favourable prognosis." (PMID 15583694, 2005). "Human epidermal growth factor receptor 3 (HER3, also known as ERBB3) is highly expressed in prostate cancer and plays a significant role in modulating the tumor microenvironment." (PMID 41228234, 2025). "In prostate cancer, CAF-derived NRG1 can promote resistance to anti-androgen therapy by stimulating ERBB2/ERBB3 heterodimers in cancer cells." (PMID 36357571, 2023). "This family of proteins has been extensively studied in breast, lung, colon and prostate cancer and its members include EGFR/ErbB1, Her-2/ErbB2, Her-3/ErbB3 and Her-4/ErbB4." (PMID 24281100, 2010). "Mechanistically, PlexinD1 activates an ErbB3/cMet-ERK/AKT-noncanonical Hh/Gli1 signaling cascade to facilitate prostate cancer growth and plasticity." (PMID 39748059, 2025). "Indeed, we found that the number of clusters expressed by specific combinations of either intra-vesicular (STAT3 and CyclinD1) or surface proteins (ERBB3, ALK, and CD81) allowed us to significantly discriminate the patients with prostate cancer from the individuals with hyperplasia." (PMID 39120316, 2024). "Although the fate of CLICs has not been tracked, Erbb3 may be transported to the nucleus of prostate cancer cells through such a mechanism and we speculate that Galectin-3 and select cargo/client proteins may make this journey together." (PMID 25869099, 2015). "In addition, ErbB3 has been shown to constitutively activate the PI3K pathway in prostate cancer cell lines, which may also lead to the constant NF-κB activation in prostate cancer cells." (PMID 20216540, 2010). "Upregulation of PlexinD1 activates the ErbB3/cMet-ERK/AKT-noncanonical Hedgehog/Gli1 signaling to promote aggressiveness, invasiveness, and therapy resistance of metastatic castration-resistant prostate cancer cells, which can be blocked by the PlexinD1-targeted protein inhibitor D1SP." (PMID 39748059, 2025).
non-small cell lung carcinoma (60 papers, 2005 to 2026). A group of at least three distinct histological types of lung cancer, including non-small cell squamous cell carcinoma, adenocarcinoma, and large cell carcinoma. "Conversely, in non-small cell lung cancer, levels of miR-205-5p were significantly elevated and acted as an oncogene by downregulating erbB3 expression." (PMID 39541878, 2024). "On the other hand, the mutation status of MUC6 and three other genes (ATR, ERBB3 and KDR) was obtained as a marker for the recurrence of non-small-cell lung cancer (NSCLC) patients." (PMID 37504272, 2023). "As an indicative example, let us consider the Gefitinib drug (CUI: C1122962), used for the treatment of locally advanced or metastatic non-small cell Lung Cancer, and the ERBB3 Gene (CUI: C0812265)." (PMID 37391722, 2023). "In non-small-cell lung carcinoma (NSCLC) cells with mutated EGFR, amplification of the MET oncogene activates prosurvival ErbB3 signaling, which allows escape from tyrosine kinase inhibition." (PMID 19019207, 2008). "Afatinib is an oral epidermal growth factor receptor tyrosine kinase inhibitor targeting the ERBB family (including EGFR, HER2, ERBB3, and ERBB4), and has been approved for the treatment of locally advanced or metastatic non-small-cell lung cancer (NSCLC) with an EGFR-sensitive mutation." (PMID 39406703, 2024). "ERBB3/ERBB4 heterodimers may also be active and relevant for disease relapse in non-small cell lung cancer, where inhibition of ligand-dependent ERBB3/ERBB4 signaling with a NRG1-blocking antibody enhanced the magnitude and duration of response to chemotherapy in various mouse models." (PMID 26745281, 2016). "In Non-Small Cell Lung Cancer (NSCLC), MET amplification drives EGFR-inhibitor resistance by activating EGFR-independent phosphorylation of ErbB3 and downstream activation of the PI3K/AKT pathway." (PMID 36432631, 2022). "In H358 non-small cell lung cancer (NSCLC) and SKBR3 breast cell lines, ErbB3 has been shown to exert function as a co-transcriptional activator for CCND1 gene expression." (PMID 27191720, 2016).
breast tumors (59 papers, 1994 to 2026). "MEDICA treatment resulted in decrease in tumor number, weight, and volume; loss of ErbB1, ErbB2, and ErbB3 in breast tumors; and decrease in lung metastatic neu cells." (PMID 32695336, 2020). "Moreover, loss of ErbB3 function has been shown to eliminate the transforming capability of ErbB2 (also known as HER-2) in breast tumours." (PMID 23835063, 2013). "Suppression of ErbB2 breast tumors by MEDICA is due to lipid raft disruption with loss of ErbB family members, including EGFR, ErbB2, and ErbB3." (PMID 32695336, 2020). "The ERBB2/ERBB3 heterodimer functions as an oncogenic unit that drives tumorigenesis; for instance, ERBB3 phosphorylation is increased in many ERBB2-overexpressing breast tumors." (PMID 31752936, 2019). "Human epidermal growth factor receptor HER3 (ErbB3), especially in association with its relative HER2 (ErbB2), is known as a key oncogene in breast tumour biology." (PMID 30367623, 2018). "The mRNA levels of ERalpha, ERbeta, epidermal growth factor receptor, ErbB2, ErbB3, ErbB4, ERRα, ERRβ, and ERRγ were determined in unselected primary breast tumors and normal mammary epithelial cells enriched from reduction mammoplasties." (PMID 28945747, 2017). "Accumulating evidences indicate that miR-205-5p is significantly downregulated in breast tumors compared with normal breast tissue and acts as a tumor suppressor directly targeting oncogenes such as Zeb1 and ErbB3." (PMID 26181203, 2015). "The combination inhibitions COX-2+ERBB2 and COX-2+ERBB3 can exceptionally exert little effect on the metastasis for breast tumor, which are reflected by the ~ 98% remaining metastasis after inhibition." (PMID 23967306, 2013). "Of note, we have previously shown that erbB3 is commonly expressed in clinical breast tumours alongside one of its ligands, heregulin β1 (HRGβ1)." (PMID 21939528, 2011). "Moreover, tyrosine-phosphorylated ErbB3 is frequently over-expressed in breast tumors that overexpress HER2." (PMID 22889873, 2012). "This led to the suggestion that ErbB3 could be an important partner of HER2 in the development of breast tumors." (PMID 22889873, 2012). "Importantly, a significant positive correlation between IRS-1 Y612 phosphorylation and total erbB3 expression was observed in these ER+ primary breast tumours." (PMID 21939528, 2011). "As the majority of these ER+ tumours were found to express low and/or negative erbB2 levels, these findings directly support our cell line work and suggest that an association between erbB3 and IRS-1 may well occur within ER+ breast tumours." (PMID 21939528, 2011). "Our cell model suggests that BCAR4-positive breast tumours are driven by ERBB2/ERBB3 signalling." (PMID 20859285, 2010). "Although overexpression of erbB3 alone may induce mammary carcinogenesis, overexpression of both erbB2 and erbB3 has been observed frequently in a transgenic mouse model that overexpresses the wild-type erbB2 protein, and in human breast tumor samples." (PMID 19590682, 2009). "Thus, further investigation which includes determination of ErbB3 expression is required as other mechanism might contribute to lapatinib cytotoxic properties on Walker 256 rat breast tumour cells." (PMID 31905843, 2019). "Patient data support this conclusion where breast tumors with decreased expression of FOXA1 were less proliferative, had reduced ERBB2/ERBB3 (HER2/HER3) expression, and increased enrichment of immune signatures." (PMID 34680352, 2021). "To do so, we had to deal with the fact that CCND1 in lung and breast tumour cell lines, EZR (Ezrin) and HMGB1 in normal Schwann cells, were the only published nuclear targets of ErbB3." (PMID 27191720, 2016). "The monoclonal antibody was found to modestly but significantly stimulate the anchorage-independent cloning efficiency of the breast tumour cell lines BT483 and T47D, both of which express the c-erbB3 protein." (PMID 8080731, 1994).
breast tumors (continued). "Similar to our in vivo results using dAd/shErbB3, oAd/shErbB3-treated breast tumors exhibited a markedly lower number of PCNA-positive cells, higher number of TUNEL-positive cells, and decreased level of ErbB3 compared to tumors that were treated with PBS or oAd." (PMID 35806132, 2022). "In both cell lines and primary patient samples, we observed consistent expression patterns of these biomarkers varies by cancer indication, such that ERBB3 and CDKN1B expression are relatively high in breast tumors while EGFR expression is relatively high in other indications." (PMID 27035903, 2016). "During the in silico simulation, all combination inhibtions except three combination inhibitions (COX-2+ERBB2 for breast tumor, COX-2+ERBB3 for breast tumor and COX-2+EPHA for colon tumor), do not have any effect on the metastasis." (PMID 23967306, 2013). "When we created a decision tree for the different luminal subpopulations, however, we observed that the gene signature of the ALDH+ population, and not the ALDH- or ERBB3- subpopulations, had the highest correlation with those obtained from basal-like breast tumours." (PMID 23088371, 2012). "This novel interaction may have clinical relevance, as immunohistochemical analysis of a small ER+ breast tumour series revealed significant positive correlations between phosphorylated IRS-1 Y612 expression and total erbB3, phosphorylated Akt and Ki-67 expression." (PMID 21939528, 2011). "Only 62 transcripts were commonly upregulated in breast tumours against both healthy breast and non-breast tissues, featuring ERBB2, ERBB3, EPCAM, and IGFR." (PMID 38306344, 2024). "Thus, if cell lines are representative of the derivative disease, one would expect to see higher levels of EGFR and lower levels of ERBB3 and CDKN1B in non-breast indications vs. breast tumors." (PMID 27035903, 2016).
colon carcinoma (57 papers, 2006 to 2025). "ErbB2 and ErbB3 are tyrosine kinase receptors that have been linked to the growth of human colon cancer and are highly expressed in HT-29 cells." (PMID 35971151, 2022). "Approximately 90% of mice with intestinal deficiency of ERBB3 developing colonic tumors, with an average of 4.2 tumors per mouse." (PMID 34843459, 2021). "Several other studies identified various somatic ERBB3 mutations in 4% of breast cancer, 10% of gastric, 1% of ovarian, 1% of colon cancer, 1% of glioblastoma; 0.5% of squamous carcinomas, and 1% of head and neck cancer." (PMID 29371993, 2017). "Some studies have suggested that increased ERBB3 protein expression in colon cancer is also associated with decreased patient survival." (PMID 26367378, 2015). "This isomer has also been reported to decrease cell growth due to a decrease in the secretion of insulin-like growth factor II (IGF-II) in Caco-2 colon cancer cells, and to cause a decrease of expression of the oncogene ErbB3 in HT-29 human colon cancer cells." (PMID 17660413, 2007). "To investigate whether ERBB3 targeting is still effective across such diverse mutations, we analyzed the effect of ERBB3 knockdown on several colon cancer cells with elevated ERBB3." (PMID 24970817, 2014). "It has been reported that NRG-1β activates ErbB-3 to promote Vemurafenib resistance in BRAF(V600E) colon cancer stem cells (CSCs)." (PMID 39052013, 2024). "The role of ERBB3 in colonic tumor development was confirmed using a distinctly different model, the AOM mouse model of CRC." (PMID 34843459, 2021). "More than half (53%) of mice with normal levels of ERBB3 treated with AOM developed one or more colonic tumors, with an average of 1.7 tumors per mouse." (PMID 34843459, 2021). "In another study, hypoxia was found to regulate cellular behavior in colon cancer by modulating the ErbB2/ErbB3 signaling pathway synergistically with the upregulation of miR-214, although in an miRNA-independent manner." (PMID 27381447, 2016). "In vitro, ERBB3 knockdown decreased cell proliferation, induced apoptosis and blocked migration of colon cancer cells." (PMID 26367378, 2015). "In vivo, the source of NRG-1β is likely to be the stromal compartment within tumors and in agreement blocking the activation of ErbB-3 significantly impacts the in vivo growth of colon cancers." (PMID 26160848, 2015). "Other investigators also have shown that heregulin is co-expressed with ErbB2 expression in colon cancer specimens and that autocrine activation of ErbB2 occurs through dimerization to ErbB3 in a colon carcinoma cell line." (PMID 25416285, 2014). "Contrary to resistance against EGFR and ERBB2 targeting, the genetic inhibition of ERBB3 results in anti-tumorigenic in HCT116 colon cancer cells harboring constitutively active KRAS and PIK3CA mutations." (PMID 24970817, 2014). "In the present study, we have analyzed the molecular mechanisms related to the anti-tumorigenic effects of the ERBB3 knockdown in colon cancer cells." (PMID 24970817, 2014). "Heregulin (HRG) is co-expressed with ErbB2 proteins in human cancer cells, and heterodimerization with ErbB3 activates ErbB2 through an autocrine mechanism in colon cancer cells." (PMID 23739740, 2013). "ErbB3 mRNA is overexpressed in the majority of human colon cancer cell lines and in human colorectal tumors." (PMID 22889873, 2012). "In addition, S. flexneri C.11 exhibited DNA-damaging activity and acted on the ERBB3 target, further activating the cascade pathway, increasing DNA damage in mice, and exacerbating colon tumor formation." (PMID 40911847, 2025). "In addition, ErbB3 downregulation or knockdown induces cell-cycle arrest and apoptosis in colon cancer cell lines." (PMID 31261874, 2019).
colon carcinoma (continued). "In addition, it has been described that flavonoids act as antioxidants and decreases the expression of ErbB2 and ErbB3 proteins in HT-29 human colon cancer." (PMID 30402124, 2018). "Previously we have shown that heregulin may contribute to angiogenesis through the phosphorylation of ErbB3 in colon cancer cell lines." (PMID 25416285, 2014). "Moreover, cell cycle arrest occurs in most colon cancer cells and is accompanied by apoptosis in a number of cell lines, supporting the potential for ERBB3 as a target in colon cancer therapy." (PMID 24970817, 2014). "An ERBB3 blockade results in the retardation of cell proliferation and elevated apoptosis in colon cancer cells, however, the mechanism leading to apoptosis is unknown." (PMID 24970817, 2014). "Therefore, the HRG/ErbB2/ErbB3 pathway is an important regulator of aberrant growth in colon cancer." (PMID 23739740, 2013). "The signalling by EGFR-ErbB3 heterodimers may play an important role in colon cancer cell lines; in fact, inhibition of AKT phosphorylation and cell proliferation by the EGFR-specific inhibitor erlotinib (Tarceva) correlated with expression of ErbB3." (PMID 22889873, 2012). "Finally, by IHC staining of TMAs, we analyzed the expression of ErbB3 in 399 colon tumor samples." (PMID 27447549, 2016). "Finally, to analyze whether blocking ErbB-3 has an effect also on colon cancer growth in vivo, we generated xenografts of Co123 and CC09." (PMID 26160848, 2015). "As further evidence of ErbB3's importance in this type of cancer, inhibition of proliferation and induction of apoptosis in HT-29 colon cancer cells by conjugated linoleic acid may be mediated by its ability to downregulate ErbB3 signaling and PI3K/ AKT pathway." (PMID 22889873, 2012). "We analyzed the effects of exogenous heregulin on ErbB2, ErbB3 and ErbB4 phosphorylation in Caco-2, DLD-1, and HCT 116 colon cancer cell lines by western blot analysis." (PMID 25416285, 2014). "In a recent study, colon carcinoma cells were transfected with a single chain antibody against HER2 and showed inactivation of HER2 tyrosine phosphorylation and reduced heterodimerization of HER2 with ErbB3." (PMID 22889873, 2012). "It has been reported that intestine-specific ErbB3 ablation resulted in almost complete absence of intestinal tumors in the ApcMin mouse model of colon cancer and that ErbB3-ErbB4 heterodimers contribute to colon cancer survival." (PMID 25416285, 2014).